PLA2G2A (phospholipase A2 group IIA)
Diseases named in the same sentence as PLA2G2A in open-access papers (continued):
Sharing a sentence is not in itself a finding about the gene and the disease.
colon cancer (5 papers, 2008 to 2025). "High PLA2G2A expression was also associated with poor prognosis in colon cancer patients harboring BRAF mutations, suggesting its potential as both a prognostic biomarker and a novel immunotherapy target." (PMID 41050070, 2025). "For example, PLA2G2A was only identified to be associated with hsa−mir−129−1 in stage I, and was previously reported to have low expression in colon cancer patients and hsa−mir−129−1 was reported to act as a tumor suppressor." (PMID 31888617, 2019). "Other markers of Paneth cells, such as secretory phospholipase A2 (PLA2G2A), MMP10 and MMP13, were also up-regulated, confirming that these cells are a cellular component of colon tumors, which is in agreement with previous reports." (PMID 26517809, 2015). "The absence of tumour-related alterations in the gene expression of PLA2G2A and PLA2G10 in human sporadic colon cancer tissues is consistent with earlier studies." (PMID 18212756, 2008). "Notably, PLA2G2A was significantly upregulated in MC and was found to promote the invasion and migration of SW480 colon cancer cells by activating the Wnt/β-Catenin signaling pathway, thus driving MC malignancy." (PMID 41050070, 2025).
coronary heart disease (4 papers, 2011 to 2025). "Increased PLA2G2A levels is a significant risk factor for coronary artery disease and are found to be highly associated with disease severity in COVID-19 patients." (PMID 36589459, 2022). "In the present study of patients with stable coronary heart disease at baseline, we found a strong determination of serum sPLA2-IIa by PLA2G2A polymorphisms." (PMID 21799821, 2011). "In the present work, we investigated the association between single nucleotide polymorphisms (SNP) in the coding gene PLA2G2A and serum levels of sPLA2-IIa in a large cohort of patients with stable coronary heart disease featuring eight years of follow-up." (PMID 21799821, 2011). "However, there are indications for the involvement of PLA2G2A in coronary heart disease and myocardial infarction, hypertrophic, and dilated cardiomyopathy." (PMID 37893006, 2023). "In humans, although polymorphisms in the Pla2g2a gene affecting sPLA2-IIA levels have been associated with metabolic disorders, such as coronary heart disease and type II diabetes, no genetic link between Pla2g2a and FTLD or other neurodegenerative diseases has been reported." (PMID 40528203, 2025).
COVID-19 (4 papers, 2022 to 2023). A disease caused by infection with severe acute respiratory syndrome coronavirus 2. "Phospholipase A2 (PLA2G2A) has been suggested as a proteomic biomarker for the occurrence of TMA, and MIS-C COVID-19 patients." (PMID 37046448, 2023).
adenoma (3 papers, 2013 to 2025). A neoplasm arising from the epithelium. "In terms of the inflammatory microenvironment, we show downregulation of Pla2g2a (2.5log2FC) in Smad4Δ/Δ adenoma." (PMID 40348815, 2025). "One example is the Pla2g2a gene (also known as Mom1), which is a known modifier of adenoma development." (PMID 23408899, 2013). "Six genes (SAA2, SAA1, CRP, SAA3P, PLA2G2A, and APOA4) listed in the heat map also indicated that the expression of PLA2G2A was limited to the adenoma tissue, following the violin plot results." (PMID 38201587, 2023).
colitis (3 papers, 2012 to 2025). Inflammation of the colon. "Previous studies found that the expressions of pro-inflammatory genes, including PLA2G2A, are upregulated in trinitrobenzene sulfonic acid-induced murine colitis." (PMID 39791167, 2025).
glioma (3 papers, 2024 to 2026). A benign or malignant brain and spinal cord tumor that arises from glial cells (astrocytes, oligodendrocytes, ependymal cells). "In comparison to other glioma subtypes, the GS2 exhibited higher expression levels of IBSP, PLA2G2A, NNMT, CA9, and MMP9, while the GS5 showed higher expression levels of CHI3L1, IGFBP2, EMILIN3, MEOX2, and PDPN." (PMID 38332637, 2024). "Functional experiments showed that PLA2G2A was highly expressed in gliomas, and its downregulation notably reduced tumor cell proliferation, migration, invasion, and growth in vivo, while reversing the epithelial-mesenchymal transition." (PMID 41849028, 2026).
Hepatic steatosis (3 papers, 2020 to 2026). Steatosis is a term used to denote lipid accumulation within hepatocytes. "Consistent with our data, a previous study shows that overexpression of human PLA2G2A results in a decrease in genes involved in hepatic triglyceride synthesis and protects against hepatic steatosis in mice fed a high-fat diet." (PMID 38232700, 2024). "These components, especially 11-deoxyalisol A and 8β-methoxyatractylenolide I, alleviated hepatic steatosis by downregulating NOS2 and PLA2G2A expression." (PMID 42075812, 2026).
idiopathic pulmonary fibrosis (3 papers, 2019 to 2023). Idiopathic pulmonary fibrosis (IPF) is a nonneoplastic pulmonary disease that is characterized by the formation of scar tissue within the lungs in the absence of any known cause. "Also, evidence from human and rat lung tissue microarray data indicated that PLA2G2A was overexpressed in patients with idiopathic pulmonary fibrosis, and in our speculation, which was most likely due to an increase in the abundance of fibroblasts." (PMID 34951074, 2022). "Interestingly, all these six dominant isoforms were found to be present only in structural cells like fibroblasts (PLA2G2A and PLA2G5), mesothelial cells (PLA2G2A) and epithelial cells (PLA2G1B, PLA2G3, PLA2G10 and PLA2G12A) that are key players in lung fibrosis." (PMID 37048117, 2023).
leukemia (3 papers, 2014 to 2022). A malignant (clonal) hematologic disorder, involving hematopoietic stem cells and characterized by the presence of primitive or atypical myeloid or lymphoid cells in the bone marrow and the blood. "Pla2g2a-deficient ATAμκTg C57BL/6 mice suppressed the initial B1a cell increase, with low/negative spontaneous leukemia/lymphoma generation." (PMID 36050343, 2022).
lung carcinoma (3 papers, 2016 to 2024). "An in vivo and in vitro studies reported declined lung cancer cells after knock down of the PLA2G2A gene." (PMID 32874197, 2020). "On the one hand, PLA2G2A inhibition has been found to decrease the levels of prostaglandin E2 (PGE2) and proliferation in human lung cancer." (PMID 39596471, 2024). "The study of Halpern and colleagues demonstrated that PLA2G2A regulates angiogenesis and metastasis through the production of PGE2, which will, in turn, upregulate the STAT3 transcription factor, activating the expression of ICAM-1, which enhances the invasion of lung cancer cells." (PMID 39596471, 2024).
pancreatic cancer (3 papers, 2022 to 2025). "To explore the mechanisms contributing to the effect of PLA2G2A on cancer cell proliferation and survival, we tested the impact of PLA2G2A on cellular fatty acid metabolism in pancreatic cancer cells." (PMID 36233022, 2022). "The elevated expression of PLA2G2A was also observed in pancreatic cancer tissues and was correlated with poor survival of PDAC patients." (PMID 36233022, 2022). "In this study, using human pancreatic epithelial cells harboring inducible K-rasG12D (HPNE/K-rasG12D) and pancreatic cancer cell lines, we found that the expression of phospholipase A2 group IIA (PLA2G2A) was upregulated by oncogenic K-ras." (PMID 36233022, 2022). "Further analysis of cellular ATP showed that a knockdown of PLA2G2A expression in human pancreatic cancer cells led to a significant decrease in cellular ATP level." (PMID 36233022, 2022). "Interestingly in pancreatic cancer, PLA2G2A + CAFs were found to attenuate the antitumor ability of tumour infiltrating CD8 + T cells." (PMID 40640495, 2025). "Based on these observations and the finding that PLA2G2A might be located on the outer mitochondria membrane, we further evaluated the impact of PLA2G2A on mitochondria function in pancreatic cancer cells." (PMID 36233022, 2022). "Treatment with tanshinone I led to a significant decrease in cellular ATP and a substantial increase in mitochondrial ROS in both pancreatic cancer cells, suggesting that inhibition of PLA2G2A could impair mitochondrial function with a decrease in ATP production." (PMID 36233022, 2022). "To further evaluate the role of PLA2G2A in PDAC, we used the pancreatic cancer datasets from SurvExpress and GEPIA, which contained RNA sequencing (RNA-seq) data and survival information on the PDAC patients." (PMID 36233022, 2022). "To further examine the relationship among K-ras, PLA2G2A, and FASN, we first used the GEPIA dataset containing RNA-seq data of pancreatic cancer from TCGA and the corresponding normal tissues from GTEx to analyze the potential correlation among these molecules in clinical samples." (PMID 36233022, 2022).
prostate carcinoma (3 papers, 2018 to 2021). A carcinoma that arises from epithelial cells of the prostate gland. "Our analysis found that dysregulation of AR signaling in prostate cancer driven by enzalutamide treatment increases the inclusion of exon-2 of the PLA2G2A gene in prostate cancer cells." (PMID 32820253, 2020). "The top up-regulated gene in prostate cancer is phospholipase A2 group (PLA2G2A), an important enzyme in inflammatory processes." (PMID 30367578, 2018). "The expression of PLA2G2A has been reported significantly increased in prostate cancer comparing to benign tissue, and it might serve as a prognostic maker for prostate cancer." (PMID 30367578, 2018).
rectal cancer (3 papers, 2020 to 2023). A primary or metastatic malignant neoplasm that affects the rectum. "PLA2G2A is associated with poor survival in patients with esophageal adenocarcinoma, glioblastoma, rectal cancer, and pancreatic ductal adenocarcinoma." (PMID 38201587, 2023). "High expression of PLA2G2A can cause short survival in human rectal cancer." (PMID 32513106, 2020). "An overexpression of the group A phospholipase A2 (PLA2G2A) dictates poor prognostic outcomes in rectal cancer." (PMID 36699376, 2022).
skin cancer (3 papers, 2022). "Remarkably, after receiving DMBA/TPA, skin tumor development was markedly lower in Pla2g2a−/− mice than in Pla2g2a+/+ mice in the cohousing (–) group, whereas cohoused Pla2g2a+/+ and Pla2g2a−/− mice displayed low tumor susceptibility, similar to the response seen in single-housed Pla2g2a−/− mice." (PMID 35076024, 2022). "In a model of carcinogen-induced skin cancer, tumor development is markedly reduced, accompanied by a reduction of degranulated mast cells in the tumor tissue, in Pla2g2a–/– mice relative to Pla2g2a+/+ mice." (PMID 35833146, 2022). "Surprisingly, cohousing of Pla2g2a–/– and Pla2g2a+/+ mice in the same cages, which results in mixing of the microbiota between the genotypes through coprophagia, abolishes the skin cancer-related phenotypes." (PMID 35833146, 2022). "To determine whether the altered microbiota observed in Pla2g2a–/– mice would be responsible for the skin cancer phenotype, we conducted microbiota-transfer studies by cohousing both genotypes, leading to exchange of the microbiota through coprophagia." (PMID 35076024, 2022). "Additionally, we found that the development of skin cancer was less marked in Pla2g2a–/– mice than in Pla2g2a+/+ mice." (PMID 35076024, 2022). "Moreover, the altered expression of Ig genes may mirror the change in gut microbiota, and lower FcεRI expression may be related to the perturbed mast cell differentiation and may thereby reduce the presence of skin cancer in Pla2g2a–/– mice." (PMID 35076024, 2022).
acute respiratory distress syndrome (2 papers, 2020 to 2025). Progressive and life-threatening pulmonary distress in the absence of an underlying pulmonary condition, usually following major trauma or surgery. "PLA2G2A (type-II secretory phospholipase A2/sPLA2), an enzyme associated with acute respiratory distress syndrome (ARDS), PLA2G2A expression was increased under both IL-6 and IL-6 trans-signalling conditions and amplified inflammatory responses in human airway smooth muscle cells." (PMID 32874197, 2020).
astrocytoma (2 papers, 2019 to 2022). "Secreted PLA2, PLA2G2A-encoded protein, was discovered to induce proliferation in astrocytoma through the epidermal growth factor receptor (EGFR), contributing to worsening the prognosis of a tumor in an inflammatory microenvironment." (PMID 36091778, 2022). "Secreted phospholipase A2 group IIA (PLA2G2A) was shown to induce phosphorylation of the EGFR to induce proliferation through a PKC-dependent pathway in human astrocytoma in vitro." (PMID 30626092, 2019).
cardiomyopathy (2 papers, 2023 to 2024). A disease of the heart muscle or myocardium proper. "In particular, the arachidonic acid metabolism gene PLA2G2A interacts with fibroblast marker genes and can potentially influence fibrosis during cardiomyopathy." (PMID 37288265, 2023). "Furthermore, genetic studies in mice demonstrated phospholipase Pla2g2a to promote myocardial injury in response to ischemia and oxidative damage, and we selected Sycp2 for its increased expression in cardiomyopathy." (PMID 39285385, 2024). "Collectively, network analysis demonstrates that the phospholipase A2 family gene PLA2G2A influences fibroblasts and may be involved in fibrosis during cardiomyopathy." (PMID 37288265, 2023).
diabetes (2 papers, 2008 to 2024). "PLA2G2A has been identified in studies focused on tumors and diabetes." (PMID 39596121, 2024).
E. coli infection (2 papers, 2016). "In a murine model of infection with Citrobacter rodentium, a pathogen that mimics Escherichia coli infection in humans, the expression of AMPs, such as RegIIIγ and Pla2g2a is dependent on STAT3 activation in the intestine." (PMID 27633343, 2016).
endometriosis (2 papers, 2015 to 2020). The growth of functional endometrial tissue in anatomic sites outside the uterine body. "The aim of this study was to determine the prevalence of the 763C>G polymorphism of PLA2G2A in women with endometriosis with respect to the control group and its relationship with the risk of endometriosis in the Iranian population." (PMID 25780526, 2015). "The aim of this study was to investigate the potential association of the 763C>G polymorphism in the secretory phospholipase A2 group IIa gene(PLA2G2A) with the risk of endometriosis in Iranian women." (PMID 25780526, 2015). "Despite the 763C>G polymorphism showing a tendency to decrease endometriosis risk, larger series are warranted to confirm this observation and to further study the association between PLA2G2A and endometriosis development." (PMID 25780526, 2015). "The present study suggests that the 763C>G polymorphism of PLA2G2A playsan important role as an independent factor in the risk of endometriosis in Iranian women." (PMID 25780526, 2015). "Overall, we observed a significant association between PLA2G2A and endometriosis risk." (PMID 25780526, 2015). "The 763C>G polymorphism of PLA2G2A is also in linkage disequilibrium with an identified functional polymorphism in this gene that may influence the risk of endometriosis." (PMID 25780526, 2015).
fibrosis (2 papers, 2010 to 2018). the formation of excess fibrous connective tissue in an organ or tissue in a reparative or reactive process. "Some of the most significantly activated canonical pathways included hepatic fibrosis/hepatic stellate cell activation (CD14, COL1A1, FGFR2, IGFBP3, MMP2, and TGFBR1), and p38 MAPK signaling pathways (CREB1, PLA2G2A, TGFBR1)." (PMID 20540791, 2010).
gout (2 papers, 2021 to 2023). A condition characterized by painful swelling of the joints, which is caused by deposition of urate crystals. "At the same time, in metabolomics, we found that the expression of PLA2G2A in the knee joint fluid of gout patients was significantly increased." (PMID 37069596, 2023). "Here, we demonstrate synovial lysosomal membrane permeability (LMP) in gouty arthritis and use synovial fluid metabolomics and proteomics to show that this effect is mediated through the activation of PLA2G2A." (PMID 37069596, 2023). "Therefore, the key mechanism of M. alba L. leaves against gout might be to suppress the inflammasomes in synovial fluids by inhibiting AKT1 by γ-Tocopherol, PRKCA by 4-Dehydroxy-N-(4,5-methylenedioxy-2-nitrobenzylidene) tyramine, and PLA2G2A by Lanosterol acetate on the RAS signaling pathway." (PMID 34502281, 2021).
heart failure (2 papers, 2022 to 2025). Inability of the heart to pump blood at an adequate rate to meet tissue metabolic requirements. "Four key biomarkers for heart failure with high diagnostic accuracy were recognized: GGT5, PLA2G2A, EPHX2, and CYP2J2." (PMID 41472876, 2025).
lymphoma (2 papers, 2022). A malignant (clonal) proliferation of B- lymphocytes or T- lymphocytes which involves the lymph nodes, bone marrow and/or extranodal sites. "Correspondingly Pla2g2a+ BALB/c and C.B17 mice showed increased B1a cells in neonatal adults and certain BCR B1 B cells generated CLL/lymphoma in old age as found in unmutated CLL in humans." (PMID 36050343, 2022). "On the other hand, in samples below PLA2G2A and RBM47, the expression cut-off, the expression of AQP1 (calculated cut-off: 30 counts, p = 0.026) divided them into the two separate subgroups comprising lymphomas and mild NSOI, respectively." (PMID 35955742, 2022). "In anti-thymocyte/Thy-1 autoreactive μκ transgenic (ATAμκ Tg) Pla2g2a+ BALB/c background C.B17 mice generated NKT2 cells that continuously control CD1d+ B1 B cells through old aging and lost CD1d in B1 B cells generating strong B1 ATA B cell leukemia/lymphoma." (PMID 36050343, 2022).
osteoarthritis (2 papers, 2025). A noninflammatory degenerative joint disease occurring chiefly in older persons, characterized by degeneration of the articular cartilage, hypertrophy of bone at the margins and changes in the synovial membrane. "A subsequent comparative analysis parallels these 9 pivotal osteoarthritis-associated genes with 3 previously identified chondrocyte-specific targets—namely, Mmp2, Hsd11b1, and Pla2g2a—revealed substantial overlap with Pla2g2a." (PMID 40880649, 2025).
Parkinson disease (2 papers, 2024 to 2025). A progressive degenerative disorder of the central nervous system characterized by loss of dopamine producing neurons in the substantia nigra and the presence of Lewy bodies in the substantia nigra and locus coeruleus. "The gene of PLA2G2A was positively enriched within hematopoietic cell lineage, complement and coagulation cascades, and cytokine cytokine receptor interaction, and negatively enriched in oxidative phosphorylation, Parkinsons disease." (PMID 41472876, 2025).
scleroderma (2 papers, 2023 to 2025). Scleroderma is a rare autoimmune connective tissue disorder characterized by abnormal hardening of the skin and, sometimes, other organs. "In our analysis of fibroblasts, FB1 was characterised as a pro-inflammatory or immune-interacting subtype by APOE, CYGB, C7, and IFGBP7 and this subset showed higher levels of CCL19 and PLA2G2A in scleroderma compared to the control." (PMID 37443817, 2023). "The presence of PLA2G2A+ fibroblasts in both CLE and scleroderma points to shared stromal alterations in autoimmune skin diseases." (PMID 40409678, 2025). "Given that GREM1+ and PLA2G2A+ fibroblasts are observed in both CLE and scleroderma, another autoimmune skin disease with mucin deposition, we examined mucin-associated gene expression across fibroblast populations." (PMID 40409678, 2025).
ulcerative colitis (2 papers, 2023 to 2025). An inflammatory bowel disease involving the mucosal surface of the large intestine and rectum. "Intestinal glandular epithelial cells in Crohn’s disease and ulcerative colitis express abundant PLA2G2A, whereas inflammatory cells lack this protein." (PMID 38130953, 2023). "PLA2G2A is increased in the colonic mucosa of patients with Crohn’s disease and ulcerative colitis." (PMID 38130953, 2023).